DERL1 (derlin 1)
Diseases named in the same sentence as DERL1 in open-access papers (continued):
Sharing a sentence is not in itself a finding about the gene and the disease.
cancer (26 papers, 2008 to 2025). A tumor composed of atypical neoplastic, often pleomorphic cells that invade other tissues. "Derlin-1 overexpression is evidently associated with cancer stage, distant metastasis, recurrence, and poor prognosis in patients with UTUC." (PMID 35205628, 2022). "BC cells have shown increased DERL1 expression during ER-stress (which is associated with solid tumor progression), while knockout of DERL1 leads to decreased cancer cell development." (PMID 35804819, 2022). "Taken together, these results implied that Derlin-1 may associate with a cancer aggressive phenotype." (PMID 35205628, 2022). "The role of Derlin-1 has also been implicated in human cancers." (PMID 28178653, 2017). "Next, the multivariate analyses revealed that high Derlin-1 staining level were significantly associated with bladder recurrence-free survival (HR = 3.62, p = 0.004), progression-free survival (HR = 4.68, p = 0.007), and cancer-specific survival (HR = 6.24, p = 0.017)." (PMID 35205628, 2022). "DERL1 is responsible for cell proliferation and promotes the progression of several types of cancers." (PMID 36774470, 2023). "Taken together, this evidence suggests the protection role of Derlin-1 expression with regard to stresses encountered during cancer cell growth and the process of tumorigenesis." (PMID 35205628, 2022). "The mechanism by which Derlin-1 regulates cancer progression still needs further investigation, including more in vitro experiments and in vivo studies." (PMID 35205628, 2022). "Previous studies demonstrate DERL1 overexpression is significantly related to cancer cell proliferation, invasion and poor prognosis." (PMID 31706287, 2019). "Our result is in accord with previous studies indicating Derlin-1 as a regulator of cancer aggressiveness." (PMID 28178653, 2017). "We report for the first time that Derlin-1 contribute to the chemoresistance of cancer cells by activation of AKT signaling, with subsequent downstream Bcl-2 elevation." (PMID 28178653, 2017). "To explore the role of Derlin-1 in this malignant tumor, first we checked its protein expression in 125 ESCC samples with follow-up data." (PMID 28903408, 2017). "The percentages of Derlin-1 overexpression in T2 and T3-T4 cancers were 50.9% and 58.1% respectively, which were significantly higher than that in Ta-T1 cancers." (PMID 28178653, 2017). "Our results are consistent with those of previous studies showing that Derlin-1 is overexpressed in various types of human cancers." (PMID 27977784, 2016). "Derlin-1 is overexpressed in various types of solid tumors and has an important function in cancer progression." (PMID 27977784, 2016). "Recently, some studies documented that the expression of Derlin-1 increased in six types of human cancers." (PMID 27977784, 2016). "The immunohistochemical staining indicated that Derlin-1 was localized in the cytoplasm in all tissues and was overexpressed in cancer tissues, especially in invasive cancer." (PMID 27977784, 2016). "Derlin-1 protein expression was significantly up-regulated in cancer tissues compared with normal mucosa (P<0.001), especially in invasive bladder cancer." (PMID 27977784, 2016). "DERL1, DERL2 and DERL3 are gene candidates for hypermethylation-associated inactivation in human cancer because a 5′-CpG island is located around their transcription start sites." (PMID 24699711, 2014). "Furthermore, high-expression Derlin-1 had notably lower bladder recurrence-free survival (p = 0.005), progression-free survival (p = 0.001) and cancer-specific survival (p = 0.001) than those with a low Derlin-1 expression level." (PMID 35205628, 2022). "Derlin-1 has recently drawn lots of attention with regard to cancer pathogenesis." (PMID 35205628, 2022). "Derlin-1, a partner of the p97 ATPase complex, played an important role in cancer progression." (PMID 29686537, 2018). "Here, we found that Derlin-1 was upregulated in 38.6% (58/150) cases of cancer samples." (PMID 28178653, 2017).
cancer (continued). "In addition, Derlin-1 overexpression induced cisplatin resistance while its depletion sensitized cancer cells to cisplatin." (PMID 28178653, 2017). "High Derlin-1 status might be a predictor of cancer aggressiveness and serve as an independent prognostic factor for ESCC patients with chemoradiotherapy." (PMID 28903408, 2017). "Derlin-1 mRNA was higher in cancer tissues than that in normal tissues." (PMID 28903408, 2017). "There is evidence in the literature implicating the role of Derlin-1 in cancer progression." (PMID 28178653, 2017). "Derlin-1 has been found to be overexpressed in several human cancers." (PMID 28178653, 2017). "Accumulating evidence has strongly demonstrated that Derlin-1 functions in cancer progression." (PMID 27977784, 2016). "Derlin-1 is overexpressed in various types of cancer and to is related to cancer progression." (PMID 27977784, 2016). "Recent studies demonstrated the function of Derlin-1 in human cancers." (PMID 24944523, 2014). "This study demonstrated that derlin-1 could protect cancer cells against ER stress-induced apoptosis, which might confer metastatic properties to cancer cells." (PMID 18205950, 2008). "Our study is the first to examine the expression of derlin-1 in human cancer." (PMID 18205950, 2008). "However, the specific molecular mechanism of Derlin-1 in cancer progression remains unclear and might vary among different types of malignancy." (PMID 35205628, 2022). "Thus, Derlin-1 overexpression could enable cancer cells to overcome apoptosis and mitotic catastrophe, which in turn facilitates therapeutic resistance." (PMID 28903408, 2017). "Additionally, derlin-1 expression may protect cancer cells from stresses encountered during tumor growth." (PMID 18205950, 2008). "Thus, Derlin-1 may have a clinical application as a novel cancer-targeting therapy." (PMID 35205628, 2022). "Fifth, we did not compare the expressions of Derlin-1 and miR-375-3p in cancer tissue and nearby normal tissue from patients with UTUC." (PMID 35205628, 2022). "In the TA of LLC‐bearing mice, a model of cancer cachexia but in C57BL/6 background, the mRNA levels of p47, Ufd2, Nploc4, and Herpud1 were all induced by about 50%, while Ufd1, Derl1, Rnf31, and Hsp90 did not change." (PMID 35611892, 2022).
tumor (23 papers, 2008 to 2025). "In the present study, we demonstrated a significant association between derlin-1 expression and axillary lymph node metastasis, suggesting that derlin-1 may be involved in the aggressive tumor growth or metastasis." (PMID 18205950, 2008). "SYVN1 and DERL1 were also significantly overexpressed in tumor tissues in the TCGA-ESCA dataset, indicating the significance of the overexpression of ERAD machinery in ESCC." (PMID 37444412, 2023). "Fourth, the expression levels of Derlin-1 and miR-375-3p were only examined in only 12 tissue samples to compare the difference between different tumor stages." (PMID 35205628, 2022). "Overexpression of some ER stress-related proteins, including Derlin-1, was examined in numerous tumor samples, and was highly correlated with tumor growth or metastasis." (PMID 35205628, 2022). "Recently, emerging studies have implied the role of Derlin-1 in carcinogenesis and tumor progression." (PMID 35205628, 2022). "Studies also report that Derlin-1 expression in BLCA tissue is higher than that in normal adjacent tissues and is associated with tumour stage, histological grade, lymph node involvement and muscle invasiveness." (PMID 36186448, 2022). "Fifty-two (52%) tumor specimens had high levels of Derlin-1 staining, and forty-eight (48%) had low levels." (PMID 35205628, 2022). "Taking this together, miR-375-3p functions as a tumor suppressive microRNA by directly targeting Derlin-1 and blocking epithelial–mesenchymal transition (EMT) in UTUC." (PMID 35205628, 2022). "For instance, inhibition of circ-TTBK2, functioned as miR-217 sponge, was found to restrain tumor proliferation via down regulating HNF1β and Derlin-1." (PMID 31895689, 2019). "Little is known about the expression of derlin-1 in tumors and the regulation of derlin-1 in tumor cells." (PMID 18205950, 2008). "A high Derlin-1 staining level was significantly correlated with the pathological stage (p = 0.019), the status of distant metastasis (p = 0.019), bladder recurrence (p = 0.012), tumor-related mortality (p = 0.001) and local recurrence (p = 0.002)." (PMID 35205628, 2022). "Previous research has reported that miR-598, miR-132, and miR-181d could target Derlin-1 and regulate tumor invasion, migration, or metastasis." (PMID 35205628, 2022). "MiR-375-3p overexpression could inversely regulate the protein levels of EMT markers, suggesting that miR-375-3p functions as a tumor suppressive microRNA to block EMT by directly binding to Derlin-1 in UTUC cells." (PMID 35205628, 2022). "In addition, we investigated the expression level of both Derlin-1 mRNA and miR-375-3p in our tumor specimens." (PMID 35205628, 2022). "In this study, Derlin-1 was much more highly expressed in invasive cancer than that in noninvasive cancer, and overexpression of Derlin-1 significantly correlated with tumor stage, histological grade, and lymph node metastasis, which is consistent with previous reports." (PMID 27977784, 2016). "We also aimed to determine whether Derlin-1, an ER-resident protein, participates in the regulation of autophagy to exert its oncogene function in tumour progression." (PMID 24944523, 2014). "Recent findings indicated that Derlin-1 has an important function in tumour progression." (PMID 24944523, 2014). "In addition, both IHC and Western blot analysis were employed to evaluate levels of derlin-1 expression in another set of tumor samples with paired normal breast tissues from 13 patients." (PMID 18205950, 2008). "Derlin-1 may function in tumour progression partially by interacting with p62." (PMID 24944523, 2014). "Our previous study demonstrated that Derlin-1 was highly expressed in CRC and significantly correlated with tumor progression." (PMID 29686537, 2018). "More importantly, overexpression of Derlin-1 had been proved to have the ability to activate PI3K/AKT and ERK pathways in tumor cells, which are the key pathways directly related to proliferation, migration, invasion, and apoptosis." (PMID 28219405, 2017).
tumor (continued). "miR-30b can inhibit the PI3K/AKT (phosphoinositide 3-kinase/protein kinase B) signaling pathway through the regulation of EGFR, AKT, Derlin-1, GNA13), SIX1, and other target genes, thus inhibiting the epithelial–mesenchymal transition process of tumor cells and promoting apoptosis." (PMID 40075907, 2025). "Notably, the expression trends of KIAA0319, DERL1, SGK3, and CLTCL1 in tumor tissues mirrored those observed in the cell lines, providing consistency between in vitro and in vivo observations." (PMID 39792732, 2025). "We further demonstrated that downregulation of Derlin-1 represses tumor cell invasion and migration rather than cell proliferation in UTUC." (PMID 35205628, 2022). "Moreover, miR-30b can inhibit the PI3K/AKT signaling pathway through the regulation of EGFR, AKT, Derlin-1, GNA13, SIX1, and other target genes, thus inhibiting the EMT process of tumor cells and promoting apoptosis." (PMID 35291564, 2022). "In tumor cells, the protein level of Derlin-1 in UM-UC-14 cells was lower than in BFTC909 cells, thus we overexpressed Derlin-1 in UM-UC-14 cells to observe whether it affected cell function." (PMID 35205628, 2022). "Besides, Derlin-1 was highly expressed in BC cell lines (um-uc-3 and T24), and the interference of Derlin-1 could reverse EMT progression, inhibit the tumor migration and invasion in T24 cells." (PMID 27977784, 2016). "In addition, derlin-1 expression is predominantly present in the cytosol of tumor cells, but not in stromal cells." (PMID 18205950, 2008).
neurodegenerative disease (6 papers, 2013 to 2024). A disorder of the central nervous system characterized by gradual and progressive loss of neural tissue and neurologic function. "We previously reported that mice with central nervous system-specific deletion of Derlin-1, which encodes an essential component for ER quality control, are useful as models of neurodegenerative diseases such as spinocerebellar degeneration." (PMID 36528738, 2022). "Results on metabolic pathways support an alteration of the Neurodegenerative Diseases and Nervous system C2 classes with the most frequently associated differentially expressed genes in the BSP (BAD, NEFH, NDUFB2, DERL1, NEFL)." (PMID 23782433, 2013). "Dysfunction of Derlin 1 and 2 have previously been related to neurodegenerative diseases." (PMID 38324617, 2024). "Although further investigation is necessary to clarify the precise mechanisms by which Derlin-1 and Derlin-2 regulate SREBP-2 activation, we propose that Derlins may be a therapeutic target to ameliorate or delay the progression of neurodegenerative diseases." (PMID 34355142, 2021).
infection (5 papers, 2016 to 2025). The state of being infected such as from the introduction of a foreign agent such as serum, vaccine, antigenic substance or organism. "Derlin-1, actin, and the U6 snRNA-associated Sm-like protein were identified and shown to be down-regulated in response to infection." (PMID 30482156, 2018). "It displayed variant-specific behavior, with the Beta variant notably upregulating DERL1 throughout infection, and similar trends seen in variants BA.1 and BA.5, while Alpha and Delta seemingly going up in middle stages of the infection and returning to their original levels." (PMID 39653747, 2024). "Indeed, QPCR analyses of HEK-293T cells that had been treated with derlin-1 or non-targeting siRNA prior to infection confirmed that the A. phagocytophilum load was higher, albeit insignificantly, in cells in which derlin-1 had been knocked down." (PMID 26973816, 2016).
neurological diseases (2 papers, 2022 to 2024). "Impaired ER function contributes to the pathogenesis of several neurological diseases characterized by cognitive dysfunction, and Derlin-1 expression in the mouse hippocampus varies across adult NSCs of different stages." (PMID 39080439, 2024).
DERL1 also shares sentences with these, for which no sentence is quoted: depression (2 papers); mental illness (2); adenocarcinoma (1); atherosclerosis (1); bipolar disorder (1); brain disorder (1); cervical squamous cell carcinoma (1); COVID-19 (1); gastric adenocarcinoma (1); gastric cancer (1); heart failure (1); large cell lung cancer (1); lung adenocarcinoma (1); mammary adenocarcinomas (1); melanoma (1); metastasis (1); myocardial infarction (1); ovarian serous cystadenocarcinoma (1); papillary thyroid cancer (1); Parkinson disease (1); prostate carcinoma (1); rectal adenocarcinoma (1); sarcoma (1); skin cancer (1); testicular cancer (1); urothelial carcinoma (1); uterine carcinosarcoma (1); viral infection (1).